ASNS (asparagine synthetase (glutamine-hydrolyzing))
Diseases named in the same sentence as ASNS in open-access papers (continued):
Sharing a sentence is not in itself a finding about the gene and the disease.
tumor (continued). "In contrast, HUH7 cells showed a higher expression of 98 metabolic targets upregulated in tumours (e.g. HK2, PKM, PSPH, GLUL, ASNS, and fatty acid synthesis enzymes ACLY, FASN)." (PMID 30176945, 2018). "HCT116 ASNS+/+ culture with E2, which increased GPER1, showed a decrease in cell growth, aligning with previous results that show HCT116 ASNS−/− tumors with high GPER1 have decreased tumor size." (PMID 38886847, 2024). "ATF4, GCN2, and ASNS were expressed at low levels in CC tissues, and all had a significant negative correlation with tumor diameter." (PMID 38844625, 2024). "Since we identified a distinct metabolic rewiring in the tumors from female R2G2 mice, and only the female tumor bearing mice with HCT116 ASNS−/− had improved survival, we then aimed to understand the transcriptional effect of ASNS deletion in the female tumor bearing mice." (PMID 38886847, 2024). "Moreover, knockdown of Rbm39 correlated with decreased Asns mRNA and arginine levels in non-tumor tissue, supporting the notion that RBM39 transcriptionally controls ASNS, which in turn promotes arginine uptake." (PMID 37804830, 2023). "We investigated the expression of SLC2A3 and ASNS in tumor and normal groups using the R package, and consistently observed high expression levels of SLC2A3 (p = 0.001) and ASNS (p = 2.708e-15) in the tumor group." (PMID 37710311, 2023). "In addition, downregulation of ASNS, inhibited SOX12-mediated CRC cell proliferation and metastasis in tumor cells overexpressing SOX12." (PMID 36090030, 2022). "This indicates that ASNS might be a novel therapeutic target for mutant KRAS CRC given its link to increased ASNS expression, Asn generation and propagation of tumor growth." (PMID 36090030, 2022). "In selected instances, DDIT3 co-expression with GOSR2 (protein transport) and ASNS (asparagine synthetase) remained coordinated, suggesting that some less-known aspects of DDIT3 activity may benefit tumor cells." (PMID 35237269, 2022). "Furthermore, DNA methylation analysis revealed that specific loci in PDX1, EIF2AK4, ASNS, DNAJB2, and FBOX6 were hypomethylated in tumor samples." (PMID 35884393, 2022). "While CB839 decreased Asp levels in tumor tissue of both mice cohorts (which either expressed ASNS or not), knocking out ASNS did not affect Asp levels upon CB839 treatment." (PMID 33101674, 2020). "In vivo tumorigenesis experiments revealed significant decreases in tumor growth, tumor weight, and Ki67-positive staining upon silencing of GLS, GOT2, or ASNS in SW480-SOX12 cells, whereas GLS, GOT2, or ASNS overexpression reversed the SOX12 knockdown-induced suppression of tumor growth." (PMID 30858360, 2019). "Finally, the subcutaneous tumor formation experiments in nude mice were conducted using the H1975 KEAP1-knockdown cells with or without ASNS overexpression treated with vehicle or MLN8237." (PMID 38521813, 2024). "Interestingly, in this study ASNS knock down did not affect the growth of the primary tumor but its metastatic behavior, which was significantly promoted, together with epithelial-to-mesenchymal transition, by enforced ASNS expression." (PMID 31998641, 2019). "Together, these findings indicate that ASNS deletion induces a robust antitumor activity and extended survival in tumor-bearing female R2G2 mice; an outcome that was absent in tumor-bearing male mice." (PMID 38886847, 2024). "Other genes, such as ASNS, EIF2AK4, ERMP1, and HYOU1, showed an increasing trend in tumor tissue, but this was not statistically significant." (PMID 35884393, 2022). "However, the downregulation of ASNS, ACAT1, and GNMT expression had no significant impact on tumor invasion." (PMID 37511510, 2023). "Of note, aspartic acid can be converted into asparagine by asparagine synthetase (ASNS), and reduction of asparagine by knockdown of ASNS or treatment with bacterial l-asparaginase reduces breast cancer invasion, circulating tumor cells (CTC), and metastasis without affecting primary tumor growth." (PMID 35071325, 2021).
cancer (66 papers, 2010 to 2025). A tumor composed of atypical neoplastic, often pleomorphic cells that invade other tissues. "This overexpression of ASNS has been linked to a mechanism of resistance to asparaginase-based therapies, which are used to target asparagine in cancer treatment." (PMID 39795937, 2024). "The catalytic activity of asparagine synthetase (ASNS) appears particularly significant, as it is implicated in metastasis and tumorigenesis, correlating with poor survival in various cancer types, including sarcomas." (PMID 38649439, 2024). "The dependency on extracellular L-asparagine in samples with loss of asparagine synthetase (ASNS) has been long studied in cancer research." (PMID 35286311, 2022). "Silencing of asparagine synthetase (ASNS), the enzyme that uses the amide group from glutamine to synthesise asparagine from aspartate has also been shown as a cause of cancer-specific auxotrophy." (PMID 31819187, 2020). "We note that NEDD9 has been implicated in cellular migration as well as in the invasion and metastasis of cancer cells, and that unregulated ASNS expression has also been linked with cancer." (PMID 24554596, 2014). "In addition, a recent study using a panel of BC cell lines revealed that glutamine deficiency leads to addiction of cancer cells to asparagine and the compensatory upregulation of Asparagine Synthetase (ASNS)." (PMID 35682953, 2022). "Cancer cells that express a low level or are deficient in Asn synthetase (ASNS) may be induced by Asn starvation." (PMID 36466394, 2022). "ASNS overexpression causes cancer cell tolerance to nutrient stress and cancer development." (PMID 32174781, 2020). "CDKN2A displayed higher mutation rates across multiple cancer types (31%), and other frequently mutated genes included LRPPRC (13%), PRKAA2 (11%), VLDLR (9%), ASNS (8%), GZMA (7%), GLS (7%), TNFRSF1A (6%), PSAT1 (5%), and PRDX6 (4%)." (PMID 37534256, 2023). "Several transcription factors were reported to regulate ASNS expression and contribute to ASNS upregulation in cancers." (PMID 37528150, 2023). "Unlike wild-type EcA, the Q59 L mutant variant, which retains L-asparaginase activity but shows undetectable glutaminase activity, was inactive against cancer cells expressing asparagine synthetase (ASNS)." (PMID 35335974, 2022). "Previous studies showed that ASNS is involved in oncogenesis in some cancer, in which it induces cell cycle arrest." (PMID 35154063, 2022). "ASNS is involved in the synthesis of asparagine, progression of the cell cycle and sensitivity to cisplatin of malignant tumors." (PMID 34692538, 2021). "ASNS, the gene encoding asparagine synthetase, has been reported as a direct target of ATF5 and CEBPB, and its over-expression is associated with cancer cell proliferation, metastasis and therapeutic resistance." (PMID 34065488, 2021). "Beyond representing markers for Bpep and Dpep activity, IL6, IL8 and ASNS have potential relevance for cancer treatment." (PMID 34065488, 2021). "We found that l-asparagine was significantly enriched in the PNI+ samples and its key enzyme ASNS overexpression accelerated nerve dysfunction and promoted cancer cells invasion in the nerve microenvironment." (PMID 33777794, 2021). "ASNS knock down or dietary asparagine restriction reduced metastasis and cancer progression while increased dietary asparagine or overexpression of asparagine synthetase drove metastatic progression." (PMID 34150624, 2021). "In mechanism, enhanced expression of NRF2/ATF4 in human ESCC cancer cells resulted in ASNS upregulation." (PMID 32174781, 2020). "It catalyzes the hydrolyzation of asparagine and glutamine, and its therapeutic rationale was historically based on the fact that cancer cells express low activity of asparagine synthetase (ASNS)." (PMID 32872391, 2020). "We found that ASNS protein level was higher in Stage III+IV cancers than that in Stage I+II cancers." (PMID 32174781, 2020).
cancer (continued). "Access to highly specific, small-molecule ASNS inhibitors that can penetrate cells will be transformative in establishing the feasibility of targeting ASNS as a new strategy to treat recalcitrant cancers." (PMID 31552298, 2019). "All of these observations strongly suggest that human ASNS is a bona fide drug target and that potent, small-molecule ASNS inhibitors will have significant clinical utility in the prevention of metastasis, and perhaps more broadly in cancer chemotherapy." (PMID 31552298, 2019). "In chemotherapeutics, asparagine synthetase (ASNS) can catalyze the glutamine- and ATP-dependent conversion of aspartic acid to asparagine and is involved in chemoresistance in cancer." (PMID 31681605, 2019). "Meanwhile, the upregulation of ASNS allows asparagine biosynthesis, making the cancer cells to be less sensitive to asparagine depletion." (PMID 28693523, 2017). "Due to the potential role of BmAsns in regulating cell development and the abnormal expression of human ASNS in cancer cells, we sought to investigate the regulatory mechanism for this gene expression using the silkworm as a model." (PMID 23382816, 2013). "Asparagine is required for protein synthesis and cellular stress responses, and cancer cells that upregulate asparagine synthetase (ASNS), the enzyme that synthesises asparagine, may better withstand the effects of radiotherapy." (PMID 39796683, 2024). "Recent studies have suggested that ASNS could have additional roles such as regulation of the mitotic spindle and immunity, playing a diverse role in cancer progression." (PMID 38474084, 2024). "However, these cancers eventually develop resistance by increasing de novo ASN synthesis through upregulation of ASNS expression." (PMID 39332495, 2024). "The expression of asparagine synthetase (ASNS) in cancer cells is notably elevated to meet the cell’s increased demand for asparagine (ASP), which plays a key role in various biological processes associated with cell proliferation and cancer progression." (PMID 39795937, 2024). "Interestingly, ASNS expression was further increased in Pkd1−/− MEFs upon glucose deprivation both at the mRNA and protein level, in line with the idea that ASNS mediates the glutamine compensatory utilization and with previous evidence in cancer." (PMID 38684863, 2024). "PHGDH may co‐express and physically interact with ASNS, a gene that catalyzes glutamine to asparagine, and other cancer‐related genes." (PMID 37387559, 2023). "Besides selecting two OSCC cell lines (HSC3 and CAL33) with different ASNS levels, knockdown or overexpression of ASNS in cancer cells through genetic modification was another reliable way to construct the in vivo PNI model." (PMID 33777794, 2021). "Silencing of ASS1 and/or ASNS may provide a selective advantage for cancer cells, allowing for diversion of aspartate towards other anabolic pathways such as nucleotide biosynthesis." (PMID 33669382, 2021). "Genes downregulated by 1E5 are overexpressed in cancer tissue, whereas ASNS, which is upregulated by 1E5, is downregulated in cancer tissue suggesting that genes altered by 1E5 are differentially expressed in tumors and highlight their potential roles in PDAC biology and disease progression." (PMID 33348693, 2020). "ASNS is an enzyme that catalyzes the ATP-dependent biosynthesis of L-asparagine from L-aspartate, an amino acid required in a large amount in cancer cells, probably for its role in maintaining cellular amino acid homeostasis, and cells lacking the enzyme depend on extracellular asparagine supply." (PMID 32872391, 2020). "Beyond EMT, evaluation of AHR-regulated expression and activity patterns revealed several targets implicated in cancer progression, including members of the matrix metalloprotease family (MMPs, MMP9 and MMP24), asparagine synthetase (ASNS) and the ATF4 transcription factor." (PMID 33214553, 2020).
cancer (continued). "Unfortunately, although ASNS inhibitor 1 might possess anti-cancer properties, its poor bioavailability curtails its usefulness for studies employing animal models of cancer and metastasis." (PMID 31552298, 2019). "ASNS expression is regarded as an important biomarker for therapeutic outcome in cancers." (PMID 30672666, 2019). "In addition, the emerging evidence has also shown that most cancer cells display high levels of ASNS expression, suggesting that the ASNS protein has an important function in cancer progression." (PMID 23382816, 2013). "Thus, we hypothesize that ASNS may serve as key molecular factor for understanding sex-biased differences in cancer incidence and survival." (PMID 38886847, 2024). "KRAS-mutant cancer cells could become adaptive to glutamine depletion through asparagine biosynthesis by ASNS; pronounced growth suppression was observed upon ASNS knockdown, indicating that ASNS might be a novel therapeutic target against tumors with mutated KRAS." (PMID 33922558, 2021). "For example, GCN2 drives the expression of asparagine synthetase (ASNS) via eIF2a/ATF4, which is required for cancer cell survival upon asparaginase treatment." (PMID 39319345, 2024). "The majority of the proteins downregulated by miR-423-5p are involved in the pentose phosphate pathway, glycolysis, and carbon metabolism in cancer (G6PH and LDHA), as well as the biosynthesis of amino acids (SHMT2 and ASNS)." (PMID 36614061, 2022). "ATF4 has been verified as a critical regulator of nutrient metabolism in many kinds of cancers, and its target genes include SLC1A5 and ASNS." (PMID 35864117, 2022). "One explanation is that compared to other cancer cells, ALL blasts express low levels of asparagine synthetase (ASNS) due to DNA hypermethylation on the gene promoter, and therefore rely on exogenous asparagine completely." (PMID 34205460, 2021). "We find that DENR•MCTS1 levels correlate with ASNS mRNA levels, a readout for ATF4 activity, across the TCGA pan-cancer set." (PMID 32938922, 2020). "In our study, ASNS overexpression enhanced clonogenicity, cell proliferation, invasion, migration, and EMT, suggesting a potential role for this protein in cancer growth and metastasis." (PMID 31681605, 2019). "Specific ASNS inhibitors are currently in development and may offer effective future treatment strategies for CRC, and indeed other cancers, in combination with asparaginase and/or autophagy inhibition." (PMID 39332495, 2024). "We finally identified 4 mRNAs (AURKA, ASNS, ESR1 and SLC39A6), 3 miRNAs (has-let-7b-5p, has-mir-10a-5p and has-mir-17-5p), and 4 lncRNAs (SNHG16, CKMT2-AS1, NEAT1 and PSMA3-AS1), all of which have been reported in cancer." (PMID 36506097, 2022). "Notably, several cancers down-regulate the activity of these pathways via silencing of ASS1 and/or ASNS expression, creating a dependence (auxotrophy) for environmental and/or stromal acquisition of these amino acids." (PMID 33669382, 2021). "A screen of >900 cancer cell lines identified aberrant ASNS promoter hypermethylation resulting in lack of ASNS protein expression in gastric and hepatic cancer cell lines." (PMID 34267184, 2021). "Our results demonstrated that, even in the absence of GLS activity, cancer cells maintain the capacity to metabolize glutamine through ASNS, which expression in these conditions is increased due to the reduction in αKG production." (PMID 34376668, 2021). "ASNS activity is expected to increase the levels of asparagine at the cost of reducing aspartate, which is limiting cancer cell growth in the absence of the importer SLC1A338,39." (PMID 33214553, 2020). "Asparagine synthetase (ASNS)-negative cancer types, which are defective in asparagine synthesis, are sensitive to L-asparaginase variants without glutaminase activity." (PMID 28750681, 2017). "The need for a dual GLS and ASNS inhibition could explain the lack of effectivity of targeting only glutaminolysis as a therapeutic approach against cancer." (PMID 34376668, 2021).
cancer (continued). "Although the relationship between cancer progression and ASNS expression is not yet well defined, it would be reasonable to suppose that ASNS expression is precisely regulated so as to prevent cancer development in normal mammalian cells, especially by a potential suppression of PcG regulation." (PMID 23382816, 2013). "Indeed, ATF4-knockout cells showed dramatically reduced levels of ASNS protein (Fig. EV7A,B), indicating a role for ATF4 not only in stress-induced expression, but also in the basal expression of this enzyme, in agreement with previous observations in cancer cell lines." (PMID 40691417, 2025). "Moreover, consistent with interference with CEBPB, CEPBD and ATF5 activities, in T98G and other non-glioma cancer lines, Dpep and Bpep suppressed expression of direct CEBPB/CEBPD targets IL6 and IL8 and of direct ATF5 and CEBPB target asparagine synthetase (ASNS)." (PMID 36831248, 2023).
infection (9 papers, 2015 to 2024). The state of being infected such as from the introduction of a foreign agent such as serum, vaccine, antigenic substance or organism. "To demonstrate that the effect of ASNS knockdown is due to decreased asparagine levels, we demonstrated that virus replication is fully rescued by adding exogenous asparagine at the time of infection in ASNS-depleted cells." (PMID 32587832, 2020). "As supplementation of asparagine was shown to fully rescue primary replication when added at the time of infection, we wanted to determine whether primary replication could be rescued following extended knockdown of ASNS, when primary replication had stalled for multiple days." (PMID 31594813, 2019). "Above results indicated that SCRV infection mainly promoted the expression of GOT1 in the early stage, and promoted the expression of MDH2, GOT2, and ASNS in CPB cells in the late stage." (PMID 37065159, 2023). "In the high-throughput screen, knockdown of ASNS inhibited HCMV primary replication, based on GFP expression, throughout the course of a single cycle infection." (PMID 31594813, 2019). "ASNS, CARS, and SC35 transcripts were significantly elevated in Huh7 cells and NPCs following infection with Asian lineage ZIKV strain P6-740." (PMID 30401782, 2018). "Consistent with cytoplasmic retention, the canonical ATF4-target genes GADD34 and ASNS were not upregulated during infection as compared with the mock or TG-treated cells." (PMID 31738790, 2019).
neurological diseases (2 papers, 2019 to 2022). "Conversely, ASNS inhibitors capable of crossing the blood-brain barrier might have clinical utility in treating ASD-linked neurological disorders arising from ASNS variants with enhanced catalytic activity." (PMID 31552298, 2019).
neurodegenerative disease (1 paper, 2019). A disorder of the central nervous system characterized by gradual and progressive loss of neural tissue and neurologic function. "Recessive mutations in the ASNS gene have been shown to cause a neurometabolic syndrome with a neurodegenerative disease course." (PMID 31123592, 2019).
ASNS also shares sentences with these, for which no sentence is quoted: triple-negative breast carcinoma (3 papers); Cerebral atrophy (2); developmental delay (2); ovarian carcinoma (2); renal clear cell carcinoma (2); acute monocytic leukemia (1); Acute myelomonocytic leukemia (1); alcoholism (1); asparagine synthetase deficiency (1); autoimmune disease (1); blood cancers (1); Brain atrophy (1); colorectal adenocarcinoma (1); early onset epileptic encephalopathy (1); ependymoma (1); epilepsy (1); essential thrombocythemia (1); gallbladder cancer (1); hyperekplexia (1); Insulin resistance (1); leiomyosarcoma (1); lipoma (1); liver diseases (1); liver fibrosis (1); lung adenocarcinoma (1); medulloblastoma (1); metabolic disorder (1); myeloid neoplasm (1); nasopharyngeal carcinoma (1); non-small cell lung carcinoma (1).
A further 6 diseases each share a sentence with ASNS in 1 paper.